STAT3 (signal transducer and activator of transcription 3)
Diseases named in the same sentence as STAT3 in open-access papers (continued):
Sharing a sentence is not in itself a finding about the gene and the disease.
cancer (continued). "STAT3 has been identified as the main transcription factor for MDSC expansion in distinct cancer models and the expression of the STAT3 target genes cyclin D1, MYC, survivin, and Bcl-xL, resulted in increased survival and proliferation." (PMID 25538893, 2014). "The mean expression of all the STATs and phospho-STATs, with the exception of phospho-STAT1(Tyr701) expression (and total STAT3 in the cytoplasm), were enhanced in their respective nodes relative to expression in the primary cancer." (PMID 24728078, 2014). "Since the initial description of the oncogenic role of STAT3 in the late 90s, much has been learned about the significance and the divergent roles of STAT3 in cancer biology." (PMID 24995504, 2014). "The signaling molecule Stat3 is constitutively activated in many human cancers and has been widely exploited as therapeutic target for cancer therapy." (PMID 24586269, 2014). "Collectively, these data suggest that constitutive IL-6 release drives IDO expression in human cancers via STAT3." (PMID 24657910, 2014). "STAT-3 is found to be constitutively active in different carcinomas and inhibition of STAT-3 activation correlates with suppression of malignant cells both in vitro and in vivo." (PMID 25296162, 2014). "An analysis of 45 prostate adenocarcinomas revealed elevated STAT3 DNA-binding activity in 37 (82%) of 45 tumors when compared to matched non-carcinoma tissues." (PMID 25268165, 2014). "Taken together, our data provide substantial evidence that dietary astaxanthin prevents the development and progression of HBP carcinomas through the inhibition of JAK-2/STAT-3 signaling and its downstream events." (PMID 25296162, 2014). "Novel compounds that inhibit STAT3 have been reported, a number of which are now in clinical trials for patients with malignant tumors." (PMID 24260055, 2013). "Accumulating evidence has reported the pro-inflammatory JAK2/STAT3 pathway plays an critical role in cancer metastasis, apoptosis and angiogenesis." (PMID 23690956, 2013). "It specifically prevents phosphorylation of Tyr 705 residue of STAT3 with IC50 ranging from 0.16 μM to 3.09 μM in various human cancer cell lines including HPAC, U87,U373, PANC1, and SK-BR-3." (PMID 24308725, 2013). "Brg1 is necessarily required to establish chromatin restructure for the activation of STAT3, especially STAT3 phosphorylation at site Try705 in various cells such as cancer cell and macrophagocyte, and for STAT3 signaling transduction." (PMID 23853776, 2013). "As the results we obtained from tests of STAT3 activation after sorafenib treatment are in line with previous studies, we have gained further insight into the mechanism of anti-cancer effects of sorafenib." (PMID 23895220, 2013). "Extensive cell proliferation studies show that simultaneous inhibition of STAT3 sensitizes the cancer cells to gefitinib-induced repression of cell growth." (PMID 24280348, 2013). "STAT3 activates pro-inflammatory pathways and plays a crucial role in modulating the epigenetic switch that links inflammation to cancer." (PMID 23750211, 2013). "Constitutive activation of STAT3 has been found in numerous types of human cancer including CRC and commonly suggests poor prognosis.Therefore, suppression of STAT3 pathway has been a major therapeutic target for treatment of cancer." (PMID 23800091, 2013). "It is activated by insulin, glucocorticoids, tumor necrosis factor-alpha (TNFα), and estrogens and induces cancer progression by activation of the JAK2/STAT3, PI3K, and MAPK pathways through LEPR-B." (PMID 23819063, 2013). "Activated STAT3 can be detected in multiple human cancers, including those of colon, skin, gastric, breast, lung and others." (PMID 23940556, 2013). "STAT family consists of 7 different subfamilies STAT1, 2, 3, 4, 5a, 5b, and 6, and STAT3 and 5 are constitutively activated in cancer cells." (PMID 23878608, 2013).
cancer (continued). "DCs obtained from myeloid-specific STAT3-conditional knockout mice were found to be affected less by cancer-derived immunosuppressive factors." (PMID 23755373, 2013). "Abnormal Stat3 protein activation has been identified in many cancers that include breast, prostate, and pancreas, as well as cancers of blood-forming cells (leukemia and lymphoma)." (PMID 23401782, 2013). "Given the oncogenic function of STAT3 and promise of inhibiting it, directly targeting STAT3 signaling cascade has been an attractive therapeutic target for drug intervention to treat cancer." (PMID 23848964, 2013). "Stattic selectively inhibits activation, dimerization, and nuclear translocation of STAT3, resulting in an increase in apoptosis rates of STAT3-dependent cancer cells." (PMID 23382914, 2013). "More importantly, STAT3 activation also has been reported to play an important role in inflammation, cancer progression and EMT induction." (PMID 23982944, 2013). "The transcription factor STAT3 is, as an oncogene, crucial for the regulation of cancer cell apoptosis and proliferation." (PMID 24179517, 2013). "Positive staining for p-STAT3 was evident in 47% of the 173 cancer specimens, and a significant positive correlation was found in cancer specimen that expressed IL-6 and p-STAT3." (PMID 23561329, 2013). "Blocking STAT3 is neither harmful nor toxic to normal cells, providing further evidence for the potential of STAT3 as a target for cancer treatment." (PMID 24179517, 2013). "Cucurbitacin I and Q were shown to specifically inhibit STAT3 phosphorylation which contributes to the proliferation of cancer cells." (PMID 23393598, 2013). "Some of these cancer-derived cytokines and chemokines impair immune cells and render them immunosuppressive via the activation of signaling molecules, such as STAT3, in the immune cells." (PMID 23755373, 2013). "Stat3 is found constitutively activated in cells transformed by the oncogenes v-Src and v-Abl, as well as in various human cancers, including hematologic, pancreas, breast, head and neck, and prostate cancer." (PMID 23577258, 2013). "Because STAT3 is one of the targets for anti-cancer drug resistance, most of investigations have been only focused on how IL-6 regulates the drug resistance in EGFR-TKI-treated cancer cells." (PMID 23592411, 2013). "As Syndecan-1 modulates the cancer stem cell phenotype via regulation of the Wnt and IL-6/STAT3 signaling pathways, it emerges as a promising novel target for therapeutic approaches." (PMID 24392029, 2013). "Signal transducer and activator of transcription 3 (STAT3) has an important role in tumorigenesis of various primary cancers and cancer cell by upregulating cell-survival and downregulating tumor suppressor proteins." (PMID 23382965, 2013). "IL-6 is a multifunctional cytokine that supports cancer cell proliferation and inhibits apoptosis through activation of STAT3." (PMID 23374147, 2013). "The roles of STAT3 in immune responses, tumor growth, and the reduction of T cell infiltration in cancer cells indicate a novel mechanism for this cellular factor." (PMID 24116074, 2013). "Amongst all the STATs signals, persistently activated STAT3 via IL-6 induced JAK2 activation promotes cancer cell proliferation, survival and invasion by promoting pro-oncogenic inflammatory pathways." (PMID 23690956, 2013). "Experimental evidence gathered in genetic mouse models over the past few years identified the transcription factor NF-κB, hypoxia inducible factor 1α (HIF-1α), and STAT-3 as the major molecular players linking inflammation and cancer." (PMID 23533994, 2013). "In the key player analysis, we found two important regulators STAT3 and hsa-let-7e in human cancers." (PMID 24205155, 2013). "Deletion of STAT3 in cancer cells resulted in reduced expression of these pro-survival genes and increased cancer cell apoptosis." (PMID 23940556, 2013).
cancer (continued). "Activation of STAT3 is known to activate an array of downstream target events to potentiate growth and malignant properties of cancer cells." (PMID 23658720, 2013). "CA inhibited cancer cell proliferation and enhanced chemosensitivity by suppressing STAT3 activation." (PMID 24260055, 2013). "Of the main targets of over-activated JAKs, STAT3 (sometimes STAT5 as well) is most concerned due to its novel roles in cancers." (PMID 23704931, 2013). "Further analysis showed that the top-ranking regulator STAT3 was significantly enriched in cancer-related FFLs, suggesting its crucial regulatory role in human cancers." (PMID 24205155, 2013). "Signal transducer and activator of transcription-3 (STAT3) is a transcription factor that integrates numerous extracellular signals to regulate cancer-promoting cellular processes." (PMID 24015205, 2013). "The mechanisms of chemoresistance are complex and studies have implicated signal transducer and activator of transcription 3 (STAT3) signaling in the chemoresistance of cancer cells." (PMID 24260055, 2013). "Clinical and experimental studies in the past provide compelling evidence for the important role of aberrant STAT3 signaling in cancer." (PMID 24170218, 2013). "Since we noticed that STAT3 binds NF-kB from the pull-down assay, we wanted to determine if hTERT expression has been changed in pSTAT3 activated cancer cells." (PMID 24386318, 2013). "Another molecular mechanism linking chronic inflammation to cancer progression involves a transcription factor known as STAT3 (signal transducer and activator of transcription 3)." (PMID 24829749, 2013). "STAT3 participates in the initiation and development of cancers by promoting cell proliferation, inhibiting cell apoptosis, promoting angiogenesis, invasion and metastasis." (PMID 24040078, 2013). "The STAT3 activation by IL-6 is well-documented to support growth, survival and metastasis of human cancer cells." (PMID 23658720, 2013). "The molecular links that connect cancer cells and TAMs are not completely known, but recent studies have demonstrated that NF-κB, STAT-3, and HIF-1 signaling pathways play key roles in this crosstalk." (PMID 23533994, 2013). "We have shown that the DAP compounds target the signal transducer and activator of transcription 3 (STAT3) signaling pathways in various cancer cells when compared to other pro-oncogenic signaling pathways." (PMID 23663277, 2013). "Maintenance of cancer cell proliferation and survival is mediated by STAT3 even after sustained c-Src inhibition through the activation of pro-survival genes." (PMID 24103426, 2013). "Taken together, these data indicate that doxorubicin-mediated inhibition of STAT3 phosphorylation is required for doxorubicin to kill cancer cells, and imatinib reverses doxorubicin resistance by preventing STAT3 phosphorylation." (PMID 23383209, 2013). "The Src kinase has also been proved to be one of major activator of STAT3 which catalyzes Tyr705 phosphorylation in some cancer cells." (PMID 23704931, 2013). "STAT3 was identified in permeabilised exosomes from the PCA cell line VCaP, and STAT3+ cMV from PCA patients was elevated when compared to non-cancer males." (PMID 26082317, 2013). "We have recently reported that alantolactone inhibits STAT3 activation in HepG2 cells, but more investigations are required to fully address the role of alantolactone and isoalantolactone on STAT3 and its regulated gene products in cancer cells." (PMID 24288468, 2013). "Here we demonstrate that the expression level of STAT3 is also important in the settings of human cancers." (PMID 23940556, 2013).
cancer (continued). "The best characterized activity of STAT3 in cancer is that of a constitutively tyrosine phosphorylated transcription factor as a result of de-regulated cytokine secretion (e.g IL-6) or mutations in tyrosine kinases including FLT3, EGFR, Src and JAK2." (PMID 24312439, 2013). "Activated STAT3 has been shown to play an important role in oncogenic transformation and progression in many human cancers." (PMID 24274066, 2013). "Curcumin inhibits the STAT3 and NF-κB signaling pathways that appear to play important roles in cancer development and progession." (PMID 23940701, 2013). "Expression of the primary-miR-21 transcript can be induced by mitogenic stimuli, such as phorbol-12-myristate-13-acetate (PMA) in several cancer cell lines, and is under positive transcriptional control of AP-1, STAT3 and NF-kB." (PMID 24098447, 2013). "Next, we prepared MDA-MB-468 cells with ectopic expression of STAT3 (left) and inoculated nude mice with the STAT3-overexpressed cancer cells." (PMID 23938089, 2013). "For example, the site is about 20 megabases off the loci for Stat3 and Stat5, two well-known signaling genes in cancer." (PMID 23308238, 2013). "Many reports today implicate STAT3-Ser in cell growth, proliferation, and survival, in the context of cancer, insulin and neurotrophin signaling, neurite outgrowth, and hypertension." (PMID 24101906, 2013). "Stat3 is a transcription factor that can promote oncogenesis, and it is commonly activated in various types of cancer." (PMID 24191246, 2013). "In contrast, STAT3 transactivation with other factors is required for full induction of the VEGF promoter in cancer cells." (PMID 24274066, 2013). "STAT3-mediated oncogenesis can be attributed by the transcriptional upregulation of multiple downstream effector genes in cancer cells such as Mcl-1, which can promote cell growth, survival, and angiogenesis." (PMID 24380387, 2013). "In this paper, we first describe the mechanism of STAT3 regulation followed by how STAT3 is involved in cancer metastasis, then we summarize the various small molecule inhibitors that inhibit STAT3 signaling." (PMID 24199193, 2013). "The Signal Transducer and Activator of Transcription 3 (STAT3) transcription factor plays a significant role in the pathogenesis of PC, being associated with malignant tumor initiation, transformation and progression." (PMID 23650499, 2013). "Nevertheless, this type of cancer still requires NF-κB within Kupffer cells (the resident macrophages of the liver), which is essential for secretion of IL-6 and activation of STAT3 in neighboring hepatocytes." (PMID 23915189, 2013). "On this basis and given the fact that IL-27 regulates STAT transcriptional factors (STAT1 and STAT3) that possess opposing activities in cancer, the impact of this cytokine on lung carcinogenesis was investigated." (PMID 24274066, 2013). "Further, evidence showed that DAPs activates cleaved caspase-3 and induces apoptotic markers of PARP in various cancer cell lines, suggesting that DAPs induce apoptosis in cancer cells by targeting STAT3 proteins." (PMID 23663277, 2013). "Constitutive over-expression or tyrosine phosphorylation of STAT3 is observed in many human cancers and supports transformation in a range of cell culture and animal models." (PMID 24312439, 2013). "STAT3 is an important transcription factor that regulates diverse physiological and pathological processes including cancer." (PMID 23940556, 2013). "In the present study, the effects of Prosapogenin A (PSA) from the traditional Chinese medicine, Veratrum, on apoptosis, the STAT3 signaling pathway and glycometabolism in cancer cells were investigated." (PMID 24179517, 2013). "The downstream targets of STAT3 signaling are well known to be mediators of cancer initiation and progression such as Cyclin D1/D2, c-Myc, Bcl-xl, and Mcl-1." (PMID 23434903, 2013).
cancer (continued). "STAT3 is frequently activated in many types of human solid and blood cancers, including breast, cancer and contributes to cancer progression." (PMID 24376586, 2013). "Signal transducer and activator of transcription 3 (STAT3) is an oncogenic protein that is constitutively activated in numerous cancer cell lines and human cancers." (PMID 23950841, 2013). "Signal transducer and activator of transcription 3 (STAT3) is a member of the STAT family of cytoplasmic proteins that is constitutively active in many human cancers." (PMID 24499623, 2013). "Luteolin promoted the degradation of Tyr705- and Ser727-phosphorylated STAT3 through interacting with Hsp90 and induced apoptosis of cancer cells." (PMID 23145121, 2012). "Persistent activation of oncogenic pathways such as MAPK, Wnt, Stat3, HIF, NF-κB and epigenetic changes are hallmark for the inflammation-induced cancer." (PMID 23217022, 2012). "As well as becoming a prognostic marker, the well-studied STAT3 pathway can therefore be targeted by a number of inhibition strategies at different levels in cancer therapy." (PMID 23554768, 2012). "Constitutive activation of STAT3 facilitates an unregulated increase in cell proliferation and reduction in cell apoptosis resulting in the development of various cancers." (PMID 22754353, 2012). "In many tumors and cancer cells, constitutive activation of STAT3 is IL-6 dependent, through either autocrine or paracrine signaling, which seems to be widely expressed in cancer cell lines." (PMID 22662257, 2012). "We also observed that STAT3 expression in cancer stem cells (CD44+CD24–/low subpopulation) of MCF-7 cells was much higher than that in MCF-7 cells." (PMID 23554768, 2012). "There is considerable evidence that wild type and mutant Rac1 and other Rho small GTPases can activate STAT3, especially within the context of cancer." (PMID 22606352, 2012). "These hpdODNs represent a basis for elaborating STAT3 DBD-specific low molecular weight compounds with anti-cancer properties." (PMID 22423663, 2012). "In many human cancers, STAT3 is constitutively activated and has been described as a novel molecular target for cancer drug discovery." (PMID 22159814, 2012). "Although IL6 is a well characterized inflammatory target gene for TNF-α, and bleomycin-induced fibrosis is ameliorated in Tnfr−/− mice, B cell infiltrates also fuel IL-6-mediated and Stat3-dependent cancer growth following the release of lymphotoxin (LT)." (PMID 22684844, 2012). "Stat3 activation within these cancer tissues and cells leads to an in increased level of anti-apoptotic proteins including Bcl-2 and Survivin." (PMID 22879872, 2012). "MCF-7 and ASPC-1 cancer cells, which expressed low level of phosphorylated STAT3, were pre-treated with XZH-5 for 2 hours followed by the addition of IL-6." (PMID 23056374, 2012). "Stat3 activity contributes to oncogenesis in breast and other cancer systems, up-regulates anti-apoptotic proteins through several pathways, enhances cell proliferation, induces angiogenesis, and suppresses immune responses." (PMID 22879872, 2012). "Possible molecular cross-talk between STAT3 and NF-κB signaling was reported previously in various cancer cells." (PMID 22984561, 2012). "Persistent STAT-3 phosphorylation has been observed in various human cancers, such as solid tumors of the stomach, colon, liver, prostate, breast, lung, and head and neck as well as blood malignancies." (PMID 22937084, 2012). "FoxM1 and STAT3 are often related to cancer and present similar consequences when overexpressed or inhibited." (PMID 23110199, 2012). "The change in the STAT3 activation pattern leads to abnormal cell proliferation or malignant transformation, so STAT3 is defined as a cancer gene." (PMID 23110625, 2012). "Given the oncogenic functions, targeting STAT3 signaling represents a molecular therapeutic approach for cancer treatment." (PMID 23056374, 2012).